IL1B (interleukin 1 beta)
Diseases named in the same sentence as IL1B in open-access papers (continued):
Sharing a sentence is not in itself a finding about the gene and the disease.
periodontitis (continued). "Many cells in the human body produce IL-1β, including monocytes, macrophages and dendritic cells and multiple studies have associated it with periodontitis, alveolar bone loss and rheumatoid arthritis." (PMID 35270581, 2022). "It has been demonstrated that there is low prevalence of the periodontitis-associated IL-1A (+4845) and IL-1B (+3954) gene polymorphisms in Chinese (2.3%) compared with that reported for Caucasians (36%)." (PMID 35855430, 2022). "Evidence shows that elevated IL-1β levels caused by pyroptosis play a direct role in the pathophysiological process of periodontitis." (PMID 36093182, 2022). "The association between periodontitis and elevated levels of Il-1β in gingival crevicular fluid has been reported." (PMID 36440291, 2022). "In some populations, the carriage rate of the IL-1B+3953 allele 2 was too low to draw conclusions about an association between IL-1B polymorphism and periodontitis." (PMID 36429405, 2022). "The overall amount of IL-1β in gingival fluid, which is associated with the intensity of periodontitis, decreases following periodontal treatment, thereby highlighting the importance of inflammatory markers." (PMID 36289921, 2022). "Activated macrophages and lymphocytes produce IL-1β, which is necessary for T cell activation and proliferation, and cooperate with IL-6 to cause periodontal tissue damage and promote periodontitis." (PMID 36710972, 2022). "Activation of the inflammatory response in plaque-stimulated periodontal tissues is the underlying pathological change in chronic periodontitis, and periodontal tissues release large amounts of inflammatory factors such as IL-1β, IL-6, IL-17, and TNF-α." (PMID 35942384, 2022). "Accordingly, a composite genotype, the so-called PST+ genotype, characterized by the simultaneous presence of IL-1A and IL-1B allele 2, was found to be related to greater severity of chronic periodontitis." (PMID 36429405, 2022). "In humans, single-nucleotide polymorphisms of the IL1B gene increase susceptibility to periodontitis, and gingival tissues from periodontitis patients show elevated mRNA expression of NLRP3 and IL1B genes." (PMID 35567665, 2022). "IL1A and IL1B polymorphisms were reported as noteworthy biomarkers for chronic periodontitis susceptibility in the evaluation of eight meta-analyses, by means of a Bayesian approach." (PMID 35454140, 2022). "IL-1β is a potent stimulator of osteoclastic activity that indirectly affects the severity of periodontitis in alveolar bone loss." (PMID 35270581, 2022). "The presented outcomes confirm the weight of the IL-1B+3953 T allele in the etiopathology of stage III grade B periodontitis." (PMID 36429405, 2022). "Our study found that GCF GM-CSF and its associated MIP-1α and IL-1β levels increase with the progression to later stages of periodontitis." (PMID 35262594, 2022). "IL-1β, on the other hand, is a notable cytokine biomarker in periodontitis risk, in terms of its development and progression." (PMID 35454140, 2022). "IL-6 and IL-1β are pro-inflammatory cytokines that are associated with chronic inflammation, periodontitis, and osteoclast bone resorption." (PMID 35628390, 2022). "Interleukin-1 beta (IL-1β) is one of the most important cytokines in causing chronic periodontitis, which is the pioneer of other cytokines in the process of inflammation." (PMID 35706460, 2022). "The present study aimed to find an association of genetic polymorphisms at IL-1A−889 and IL-1B+3953 loci in Polish patients with stage III grade B periodontitis and periodontally healthy subjects." (PMID 36429405, 2022). "Complex genotypes consisting of at least one IL-1A−889 and IL-1B+3953 T allele occurred significantly more frequently in subjects with periodontitis." (PMID 36429405, 2022).
periodontitis (continued). "We find from the database DisGeNET that 4 high-ranking target proteins, Interleukin-1 beta (3rd), Caspase-1 (3rd), Caspase-3 (3rd) and Matrix metalloproteinase-9 (3rd), are associated with the top disease Periodontitis (1st)." (PMID 35249529, 2022). "We evaluated the expression levels of known proinflammatory cytokines associated with periodontitis (IL-1β, IL-6, and TNF-α)." (PMID 36319994, 2022). "They concluded that as a single marker IL-1β showed the best diagnostic value with 90% sensitivity and 76% specificity for discriminating periodontitis subjects from healthy subjects." (PMID 35368315, 2022). "Comparative levels of salivary IL-1β can be potentially used as a diagnostic tool for periodontitis identification and disease progression along with clinical parameters." (PMID 35270581, 2022). "The results showed that bee venom (100 μg/kg) treatment reduced inflammatory bone loss-related periodontitis induced by P. gingivalis and reduced the expression of IL-1β and tumor necrosis factor (TNF)-α in vivo." (PMID 35624686, 2022). "Numerous inflammatory cytokines, including interleukin-1β (IL-1β), regulate periodontitis pathophysiology and cause periodontal tissue destruction." (PMID 34504537, 2021). "Clinical evidence shows that IL-1β, a pro-inflammatory cytokine, is raised and contributes to periodontitis susceptibility." (PMID 35046930, 2021). "Emerging experimental and clinical studies have demonstrated that TNF-α, IL-1β, and IL-6 are associated with the initiation and progression of periodontitis." (PMID 34395635, 2021). "Periodontitis is associated with several host responses, including expression of IL-1β, IL-6, and TNF-α in response to oral bacteria." (PMID 34592963, 2021). "The clinical report that demonstrated increased ROS in inflamed periodontal tissue 27 implicated ROS in IL-1β-related pathogenesis in periodontitis following P. nigrescens infection." (PMID 33390812, 2021). "IL-1β is a multifunctional cytokine with diverse biologic activities implicated within the pathophysiology of periodontitis and peri-implantitis." (PMID 33726736, 2021). "Pharmacological inhibition of caspase-4 or IL-1β antibody blockade in a rat periodontitis model lead to the significantly reduced loss of alveolar bone and periodontal ligament damage." (PMID 33869229, 2021). "Longitudinal studies are required to investigate the function of NLRP3 (rs4612666) and IL-1β (+3954) gene polymorphisms as therapeutic markers for periodontitis and coronary heart disease." (PMID 34501201, 2021). "Previous studies have investigated the pathogenesis of periodontitis and its association with the inflammatory cytokines IL-1β, IL-4, IL-6, IL-10, interferon-γ (IFN-γ), and TNF-α39." (PMID 34764408, 2021). "The question of this study is as follows: in aging adults, do chronic apical periodontitis lesions as biomarkers have a risk effect on the immunoexpression of pro-inflammatory cytokines (IL-1β, IL-6 and TNF-α) compared to adults?" (PMID 35053012, 2021). "At last, treatment with MCC950 significantly suppressed alveolar bone loss with reduced IL‐1β activation and osteoclast differentiation in ligature‐induced periodontitis." (PMID 33382502, 2021). "Polymorphisms of IL-10 have been associated with those of tumor necrosis factor α IL-1α, IL-1β and IL-1RA in periodontitis." (PMID 34069916, 2021). "IL-1β −511C>T polymorphism had a very strong relationship in the periodontitis risk with OR (95% CI), 0.50 (0.30–0.71)." (PMID 35046930, 2021). "Susceptibility of individuals to develop periodontitis was found to be associated with IL1β gene (3953/4C>T) polymorphisms." (PMID 33081038, 2020). "Although literature showed a lack of studies in the field of epigenetic factors related to periodontitis, a strong association has been found between IL-1B and TNF-α polymorphism and persistent apical periodontitis." (PMID 32684934, 2020).
periodontitis (continued). "According to several studies, the association between periodontitis and high levels of IL-1β, TNF-α, and MMP-8 in the GCF is well established." (PMID 32064567, 2020). "Previous studies showed an association between PD and CAL and GCF IL-1β levels in patients with severe periodontitis and reported a significant reduction in this cytokine after SRP." (PMID 33218047, 2020). "Genetic polymorphisms of IL-1α and IL-1β are likely to be related to an individual’s genetic susceptibility to periodontitis." (PMID 33081038, 2020). "IL-1A allele 2 and IL-1B+3953 allele 2 genotypes were recognized as strong indicators for severe periodontitis in an adult populations." (PMID 33343358, 2020). "Parkhill reported that IL-1β, IL-1-Receptor Antagonist and IL-1β genotype combined with smoking in Caucasians are risk factors for early onset periodontitis." (PMID 33343358, 2020). "Further studies highlighted the ability of IL1β to identify subjects at risk of developing progressive periodontitis and an association of increased IL1β concentration in saliva with increasing rate of bone loss and CAL." (PMID 33081038, 2020). "Diagnostic model of Grade C periodontitis was constructed combining IL-1β and IL-9 GCF levels and showed an accuracy of 0.92 with high sensitivity (0.94) and specificity (0.89)." (PMID 33218047, 2020). "The authors of another study found the associations between IL-1α gene −889C/T and IL-1β gene +3953C/T polymorphisms and early-onset periodontitis in African American and Caucasian populations." (PMID 33327639, 2020). "IL-1β is an important mediator of the inflammatory response and the pathophysiology of periodontitis and is associated with cell proliferation, differentiation, and apoptosis." (PMID 31308830, 2019). "The main cause of periodontitis, bacterial plaque, triggers production of key cytokines, such as IL-1β and TNF-α, from macrophages." (PMID 31027223, 2019). "Development of chronic periodontitis is linked to Th1 lymphocytes that produce IFNγ and IL-1-β and Th17 lymphocytes that produce IL-17A." (PMID 31849924, 2019). "SOCS3 deficiency results in increased alveolar loss with high levels of IL-1β, IL-6, and IL-8 in periodontitis." (PMID 31304055, 2019). "If more results in various populations would be accumulated in further studies, the relation between IL-1β polymorphism (rs16944) and chronic periodontitis would be clarified and that would help improving clinical prognosis." (PMID 30647799, 2018). "IL-1β polymorphism (rs16944) is one of the most commonly investigated polymorphism regarding susceptibility to chronic periodontitis." (PMID 30647799, 2018). "And to perform meta-analysis, studies about IL-1β polymorphism (rs16944) and chronic periodontitis were searched in PubMed, Embase, Google Scholar, and Korean Studies Information Service System (KISS) electronic databases until July 2017." (PMID 30647799, 2018). "The subgroup analysis stratified by ethnicity showed a weak association between the IL-1β polymorphism (rs16944) and chronic periodontitis in the Caucasian population (recessive model, OR = 1.34, 95% CI = 1.017–1.758, P = 0.037)." (PMID 30647799, 2018). "The purpose of this study was to evaluate the association of IL-1β polymorphism (rs16944) and the susceptibility to chronic periodontitis from a new case-control study and then to further perform an updated meta-analysis to derive a more precise conclusion." (PMID 30647799, 2018). "Several studies have investigated the potential relationship between IL-1β polymorphism (rs16944) and susceptibility to chronic periodontitis; inflammatory process is involved, but conclusions is still controversial." (PMID 30647799, 2018). "We evaluated the association between IL-1β polymorphism (rs16944) and chronic periodontitis in the present case and control study." (PMID 30647799, 2018).
periodontitis (continued). "A statistically meaningful association was detected with IL-1β polymorphism (rs16944) in the Caucasian population, but it is difficult to describe a strong association with chronic periodontitis due to insufficient statistical power." (PMID 30647799, 2018). "We also evaluated the relationship between IL-1β polymorphism (rs16944) and chronic periodontitis using meta-analysis." (PMID 30647799, 2018). "These in vivo data further confirm that V1 SNP is associated with the pathogenesis of periodontitis including alveolar bone loss and IL-1β expression." (PMID 30206230, 2018). "To obtain more reliable results on the relationship between the IL-1β polymorphism (rs16944) and the susceptibility to chronic periodontitis, we performed a case-control study and meta-analysis with all eligible studies." (PMID 30647799, 2018). "Two recent meta-analyses reported distinct effects on susceptibility to chronic periodontitis of single nucleotide polymorphism (SNP) rs1143634 versus rs16944 in IL-1B gene." (PMID 29023524, 2017). "The likelihood of periodontitis in patients with IL-1A and/or IL-1B polymorphism was lower when IL-1RN polymorphism was also present in comparison to IL-1A and/or IL-1B polymorphisms alone." (PMID 29023524, 2017). "In our study population, logistic regression analysis showed that polymorphism in IL-1A and/or IL-1B gene was strongly associated with generalized periodontitis (GCP or GAgP)." (PMID 29023524, 2017). "The likelihood of periodontitis (aggressive + chronic) was significantly higher for patients with IL-1B polymorphism (OR = 23.47; 95%CI [4.65–111.61] for GAgP and OR = 6.23; 95%CI [1.25–30.98] for GCP)." (PMID 29023524, 2017). "Many researchers have attempted to find useful biomarkers such as TNF-α, IL-10, IL-17, IL-12, and IL-1β in saliva that are associated with periodontitis to help predict or diagnose T2DM." (PMID 29109737, 2017). "The increased ratio IL-1β/IL-10 in gingival crevicular fluid can be associated with the progression of aggressive periodontitis." (PMID 28662142, 2017). "IL-1A and IL-1B gene polymorphisms have been considered a risk factor for periodontitis progression in populations of European descent due to a resulting overproduction of pro-inflammatory IL-1α and IL-1β, respectively." (PMID 29023524, 2017). "Blocking of IL-17 or its associated IL-23 decreased periodontitis progression in Cd18 knockout mice and caused lower levels of pro-osteoclastogenesis cytokines IL-1β and RANKL." (PMID 29163477, 2017). "Polymorphism in the IL-1A and/or IL-1B gene was associated with a greater likelihood of the presence of periodontitis when the two types (GCP + GAgP) were considered together." (PMID 29023524, 2017). "Rgps-mediated PAR2 activation enhanced the biosynthesis of prostaglandin E2, IFN-ɤ, IL-1β, and IL-6, which led to accelerated alveolar bone loss in experimentally-induced periodontitis in mice." (PMID 28589098, 2017). "In a recent meta-analysis of 53 studies deduced that chronic periodontitis is significantly associated with IL-1A -889 C/T and IL-1B +3954 C/T polymorphisms, whereas a weak association was also detected between IL-1B -511 T/C and chronic periodontal disease." (PMID 28624837, 2017). "Nevertheless, a recent study with a bigger sample of preconception women with periodontitis showed a positive association between elevated concentrations of IL-1β, β-glucuronidase, and TNF-α in saliva and serum." (PMID 29017560, 2017). "Lots of studies have investigated the importance of genetic polymorphisms (e.g., MCP-1, S100A8, IL-1α, IL-1β, and N-formyl peptide receptor) in aggressive periodontitis." (PMID 28018430, 2016). "A combined genotype with single nucleotide exchanges in the IL-1A and IL-1B gene was found to be associated with an increased risk of periodontitis." (PMID 26595831, 2016).
periodontitis (continued). "The expression level of IL1B is positively correlated with attachment loss, and this cytokine is associated with continuous tissue destruction in periodontitis." (PMID 27391467, 2016). "Several previous studies have demonstrated strong associations between the high frequency of genetic polymorphism in IL1β and the development of severe chronic periodontitis." (PMID 25483140, 2015). "Some studies have shown that IL-1β polymorphisms are associated with type 2 diabetes and chronic periodontitis." (PMID 26496436, 2015). "Genes known to be associated with peri-implantitis and periodontitis were tested for their presence in our case group; IL-1A, IL-1B, and TNF all appeared in our dataset." (PMID 24921256, 2014). "Because elevated IL-1β levels are implicated in CP progression 18, including primate model evidence that IL-1 blocking drugs reduce periodontitis 19, the role of IL1 variants in severe CP has biological plausibility." (PMID 24702466, 2014). "Production of IL-1β was significantly higher in patients with periodontitis carrying the CC genotype IL-4 -590C/T variant after stimulation with T. forsythia and in the unstimulated culture (P < 0.05)." (PMID 25530681, 2014). "Our findings are in fact at variance with other investigations showing that gene variations of INF-γ, IL-1β and IL-6 were associated with periodontitis." (PMID 24274085, 2013). "Previously, variations in the genes that regulate the IL-1 response have been associated with periodontitis; allele 2 of IL-1α−889 and IL-1β+3954 was found to be associated with severe chronic periodontitis in nonsmokers." (PMID 23691333, 2013). "IL-1α and IL-1β upregulate prostaglandin E2 and matrix metalloproteinase and, together with these components, promote the loss of connective tissue and bone in periodontitis lesions." (PMID 23691333, 2013). "Increased IL-1β expression has been consistently detected in both samples and was associated with periodontitis severity, and IL-1β decreased after treatment." (PMID 22315682, 2012). "IL-1β in gingival crevicular fluids of patients with periodontitis decreases significantly after initial periodontal therapy, indicating that IL-1β is associated with periodontitis." (PMID 23251684, 2012). "In the current study, the IL-1A C[−889]T and IL-1B C[3954]T polymorphisms showed strong association with sever periodontitis in the TT versus CT + CC genotype contrast (recessive model)." (PMID 22778957, 2012). "The purpose of this study was, therefore, to assess the association between the IL-1A C[−889]T and IL-1B C[3954]T polymorphisms and sever chronic periodontitis among Yemenis based on haplotype analysis." (PMID 22778957, 2012). "Using genotyping IL-1 test, a pilot study was conducted on 32 Syrian patients with aggressive periodontitis (AgP) and 35 healthy controls to investigate the association between the IL-1α(−889), IL-1B(+3953) gene polymorphisms and AgP among schoolchildren." (PMID 22203911, 2011). "The SNP IL1B +3954 (+3953) was initially proposed as risk factor for periodontitis among Caucasians." (PMID 20339487, 2010). "Clinical studies have consistently demonstrated elevated levels of NLRP3, caspase-1, IL-1β, and IL-18 in the gingival tissues and gingival crevicular fluid of patients with periodontitis, correlating with attachment loss, probing depth, and bleeding on probing." (PMID 41596738, 2026). "It has been proposed that the elevated expression of IL-1β in psoriatic patients may underlie the increased incidence of tooth loss, alveolar bone resorption, and periodontitis reported in this population." (PMID 40731810, 2025). "Pro-inflammatory factors such as NLRP3 and IL-1β, which are linked to local inflammation in periodontitis, may stimulate systemic inflammation and contribute to the development of hypertension." (PMID 40572711, 2025).